TLR4 (toll like receptor 4)
Diseases named in the same sentence as TLR4 in open-access papers (continued):
Sharing a sentence is not in itself a finding about the gene and the disease.
uterine inflammatory disease (1 paper, 2022). "TLR4 exists in the ovary and reproductive tract, and TLR4 is also involved in inducing apoptosis of ovarian granulosa cells in uterine inflammatory diseases." (PMID 35531876, 2022).
vaginal cancer (1 paper, 2022). A primary or metastatic malignant neoplasm involving the vagina. "For instance, a recent report shows that the expression of toll-like receptor 4 (TLR4) is closely related to HPV infection and vaginal cancer cell growth, with TLR4 signaling contributing to the formation of a local immunosuppressive microenvironment in the vaginal area." (PMID 36116940, 2022).
varicocele (1 paper, 2021). A condition characterized by the dilated tortuous veins of the spermatic cord with a marked left-sided predominance. "In WT and TLR4 KO varicocele animals administered with PEA-um, a substantial reduction of NLRP3 expression was demonstrated." (PMID 33668991, 2021). "PEA-um treated varicocele WT and TLR4 KO animals showed a significant reduction of TGF-β3 expression." (PMID 33668991, 2021). "Another group (WT, PPAR-α KO, and TLR4 KO) underwent surgical varicocele and was treated with vehicle or PEA-um (10 mg/kg i.p.)for 21 days." (PMID 33668991, 2021). "PPAR-α expression was reduced in WT and TLR4 KO varicocele animals treated with vehicle, while PEA-um administration restored PPAR-α expression to basal levels in both groups." (PMID 33668991, 2021). "Treatment with PEA-um reduced p-ERK 1⁄2 expression in WT and TLR4 KO varicocele administered animals, while in PPAR-α KO varicocele mice treated with PEA-um, the reduction in p-ERK 1⁄2 expression was abolished." (PMID 33668991, 2021). "Conversely, varicocele induction increased TLR4 expression in WT and PPAR-α KO mice, compared to sham." (PMID 33668991, 2021). "On the contrary, in WT, PPAR-α KO, TLR4 KO varicocele mice, and mice treated with vehicle, tubules showed a discontinuous epithelium, a reduced MTD, and a low Johnsen’s score." (PMID 33668991, 2021). "TLR4 KO varicocele mice treated with PEA-um showed a normal germinal epithelium with many spermatids and mature spermatozoa; only a mild edema was present in the extratubular compartment." (PMID 33668991, 2021). "A significant increase in NLRP3 expression was detected in vehicle WT, PPAR-α KO, and TLR4 KO varicocele mice, compared to the sham operated animals of the same groups." (PMID 33668991, 2021). "Moreover, our immunohistochemical and Western blot analyses revealed a significant decrease in PPAR-α expression in the testes from WT and TLR4 KO mice subjected to varicocele, when compared to sham groups." (PMID 33668991, 2021). "Indeed, PEA-um administration increased PPAR-α expression in varicocele WT and TLR4 KO mice." (PMID 33668991, 2021). "TLR4 expression was increased in WT and PPAR-α varicocele animals treated with vehicle, while PEA-um treatment reduced TLR4 expression in WT mice." (PMID 33668991, 2021). "Overall, our results suggest that, in line with our previous study, PEA-um, via a TLR4-dependent pathway, selectively restores the expression of claudin-11 and occludin and reduces the expression of TGF-β3, p-ERK 1/2 and NLRP3 in varicocele mice." (PMID 33668991, 2021). "PEA-um treatment downregulated TLR4 expression in varicocele WT mice, while in PPAR-α KO mice TLR4 expression was not modified by PEA-um administration." (PMID 33668991, 2021). "Furthermore, varicocele induction led to an increase in NLRP3 expression in WT and KO animals, with a marked reduction in TLR4 KO mice." (PMID 33668991, 2021).
vasomotor rhinitis (1 paper, 2012). Inflammation in the nasal cavity mucosa that results from the abnormal regulation of the blood flow in the nose. "A similar co-localization of TLR4/TLR was also observed in vasomotor rhinitis." (PMID 22577387, 2012).
tumor (1,706 papers, 2006 to 2026). "Using both human and mouse in vitro assays and an in vivo mouse tumour model, we demonstrate a TLR4-dependent causative role for increased ratios of hexa-acylated LPS in the gut in enhancement of anti-PD-1-mediated anti-tumour responses." (PMID 39929976, 2025). "Both RAGE and TLR4 are upregulated in tumor-associated macrophages (TAMs) and serve pro-inflammatory purposes for sustained inflammation, angiogenesis, and tumor progression." (PMID 41188771, 2025). "Activation of STAT3 signaling promotes the secretion of S100A8/A9, a heterodimeric calcium-sensing damage-associated molecular pattern (DAMP), which binds to Toll-like receptor 4 (TLR4) on adjacent tumor cells." (PMID 40948745, 2025). "Specifically, SAA can bind to receptors on the surface of tumor cells and tumor-associated macrophages, such as TLR4, triggering phosphorylation and nuclear translocation of NF-κB." (PMID 41216199, 2025). "TLR4 engagement is particularly important in this process and can even cause repolarization of tumor-associated M2-like cells." (PMID 40649953, 2025). "Mice deficient in TLR4 demonstrate protective effects against DSS‐induced UC‐associated neoplasia, indicating that TLR4 promotes tumorigenesis by modulating colonic epithelial cells' innate immune signaling pathways." (PMID 41164267, 2025). "Third, we established strong associations between TLR4/MyD88 pathway activation and aggressive tumor features, including perineural invasion, high-grade tumor budding, and lymph node metastasis." (PMID 40703545, 2025). "Multiple studies have shown that TLR4 expression in the tumor microenvironment is tightly linked to the immune defense." (PMID 40999508, 2025). "A significant finding is the identification of TLR4 as a critical molecule associated with tumour progression." (PMID 40696496, 2025). "For example, specific TLR-4 agonists induce the polarization of tumor-associated macrophages (TAMs) toward the M1 phenotype, thereby enhancing the body's immune-mediated cytotoxicity against tumor cells." (PMID 40404908, 2025). "TLR-4 is not only expressed in immune cells but also in various malignant tumor cells, especially inflammation-associated tumor cells, and plays a crucial role in tumor formation, development, and chemoresistance." (PMID 40404908, 2025). "It is estimated that 20% of mononuclear inflammatory cells express TLR4 in the breast tumor microenvironment, which is associated with tumor aggressiveness." (PMID 40647480, 2025). "Upon tumor colonization, the immunogenicity of DB1 activated Toll‐like receptor 4 (TLR4) signaling in tumor‐associated macrophages (TAMs), promoting interleukin‐10 (IL‐10) secretion and reshaping the tumor immune microenvironment." (PMID 40878391, 2025). "TLR4 expression has been observed in various cancer cells and implicated in promoting tumor cell survival, proliferation, and metastasis." (PMID 41332426, 2025). "TLR4 signaling has been implicated in the tumor microenvironment, where it can influence tumor progression, metastasis, and immune evasion." (PMID 39976020, 2025). "TLR4 signalling has also been shown to induce polarisation of tumour‐associated macrophages (TAMs) toward the M2 phenotype, which typically exhibits immunosuppressive, pro‐angiogenic, and tumour‐promoting characteristics." (PMID 40696496, 2025). "Consistently, TLR4 deficient TAMs showed a decreased NF-κB activity, and a reduced production of inflammatory and angiogenic factors, thus limiting tumor growth in vivo." (PMID 38397187, 2024). "Saponins and polysaccharides can regulate the phenotypes of tumor-associated macrophages (TAMs) by influencing signaling pathways such as TLR4/AMPK/NF-κB/STAT3 and directly modulating the expression of CD206 and VEGF." (PMID 38792234, 2024).
tumor (continued). "Gut sterilization obtained by the administration of antibiotics decreased LPS serum levels and was associated with an effect on tumor size and number similar to TLR-4 mutation, further confirming that gut microbiota-driven inflammation favors HCC progression." (PMID 39064815, 2024). "In the context of immunotherapy, the tumor-intrinsic NLRP3-heatshock protein 70 (HSP70) toll-like receptor 4 (TLR4) axis has been associated with disease hyper-progression and survival in patients undergoing anti-PD-1 immunotherapy." (PMID 39769450, 2024). "In the same vein, TLR4 deficiency at metastatic sites decreases tumor cell adhesion, thereby linking the TLR4 signaling cascade response to enhanced metastatic adhesion and peritoneal spread." (PMID 38685971, 2024). "TLR4 signaling in tumor cells has been implicated in promoting immune escape and progression, with TLR4-triggered resistance to apoptosis considered a contributing mechanism." (PMID 38930793, 2024). "Toll-like receptor-4 (TLR4) has been implicated in tumor progression, though the role of TLR4 in Ahsg uptake has only recently been explored." (PMID 39684629, 2024). "TLR4 is highly expressed in a variety of malignant tumor cells and is associated with clinicopathological features and prognostic indicators." (PMID 38463226, 2024). "The role of TLR4 has been reported in several tumor types and has been implicated in both pro- and anti-tumorigenic processes." (PMID 39684439, 2024). "A new vaccine adjuvant system combining the T-cell costimulatory molecule SA-4-1BBL with the TLR4 agonist monophosphoryl lipid was evaluated for its ability to enhance the effects of tumor-associated antigens." (PMID 39238498, 2024). "Activation of the TLR4/NF-κB pathway is associated with tumor progression, and its inhibition can exert anti-tumor effects, whereas activation promotes metastasis or recurrence of tumor cells." (PMID 39295870, 2024). "TLR4 is more highly expressed in HPV-independent tumor tissue, and the number of “star_lost” variants is greater in “African and African-American populations." (PMID 39208235, 2024). "In this instance, secreted cathepsin-K can bind to TLR-4 and stimulate tumor-associated macrophages to adopt M2 polarization and secrete IL-10 and IL-17, promoting invasion and metastasis." (PMID 39624362, 2024). "This is due to alteration in toll-like receptor 4 (TLR4) signalling pathways, which lead to a switch of tumour-associated macrophages toward the protumoural M2-like phenotype, as well as to a reduction of T cell-mediated immunity." (PMID 38396870, 2024). "In tumor-associated muscle wasting, eHSP70 and TLR4 were identified as major mediators of cell regeneration." (PMID 37511459, 2023). "Noteworthily, TLR4 polymorphisms that reduce its ability to bind HMGB1 reduce tumor antigen processing and presentation by dendritic cells." (PMID 36831435, 2023). "A review of the global literature focused on the influence of TLR4 gene polymorphisms and expression on the course of various cancers (tumor proliferation, differentiation, metastases, prognosis, and patient survival)." (PMID 37370894, 2023). "TLR4-induced TGF-β expression has also been associated with the transformation of fibroblasts into cancer-associated fibroblasts in the tumor microenvironment, facilitating cancer cell proliferation and tumor growth." (PMID 36932197, 2023). "The carcinogenetic role played by the chronic activation of TLR4 has already been linked to tumor proliferation and mononuclear antitumor activity inhibition in HCC, gastric carcinoma, and colorectal carcinoma." (PMID 36766711, 2023). "TLR-4 is mainly activated by pathogen-associated molecular patterns (PAMPs) in a tumor microenvironment." (PMID 37630236, 2023). "We show that the mH2A1 splicing isoform mH2A1.1 accumulates in MDS-MSCs, correlating with the expression of the Toll-like receptor 4 (TLR4), an important pro-tumor activator of MSC phenotype associated to a pro-inflammatory behavior." (PMID 37852977, 2023).
tumor (continued). "Pathogenic bacteria in the tumor can activate TLR4 of mesenchymal cells and the MYD88 pathway, releasing the inflammatory factor IL-23, which in turn activates IL-17A, IL-6, and IL-22 to promote the development of CRC." (PMID 35914737, 2023). "TLR4 activation can not only cause antitumor immunity but also, conversely, promote immunosuppression and influence tumor growth." (PMID 37370894, 2023). "A high TLR4 immunoexpression associated with a higher CD3–CD8 tumor–stroma index (p = 0.022, chi-square test), with a positive correlation (rs = 0.098; p = 0.029)." (PMID 36649244, 2023). "In HCC, TLR4 is overexpressed and has been associated with tumor growth, metastasis, and resistance to chemotherapy." (PMID 37896221, 2023). "This study demonstrates the therapeutic interest to use TLR4 agonists to produce immune-mediated antitumor response for tumours associated with TLR4 activation." (PMID 35990515, 2022). "By contrast, TLR4−/− macrophages remained Bcl6lowLy6Chigh phenotype during the whole period of tumorigenesis, implying that induction of TLR4 and subsequent Bcl6 were associated with macrophage tumor-promoting activity." (PMID 36542153, 2022). "There are already controversial reports of reduced tumor growth and improved survival in TLR4-deficient mice." (PMID 36224342, 2022). "Considering that tumor niches were frequently populated with macrophages, a key player in tumor immunity, we postulated that intratumoral macrophages were related with differential tumor growth in TLR4 sufficient or deficient mice." (PMID 36542153, 2022). "We observed that high tumor expression of TLR4 was associated with improved overall survival (p = 0.027), whereas low tumor expression of STMN1 was associated with improved overall survival (p < 0.001), both by Kaplan-Meier survival analysis." (PMID 35874727, 2022). "LPS-mediated induction of cytokine transcription in PC3 cells was TLR4- and Myd88-dependent, suggesting that pathogen-associated molecular pattern recognition mechanisms are comparable between tumor and immune cells." (PMID 36539532, 2022). "High risk HPV promote upregulation of IL6 and TLR4, resulting in an inflammatory environment that can contribute to tumor development." (PMID 35468924, 2022). "For example, the imbalance of gut microbiota contributes to the metastasis‐related secretory protein cathepsin K secretion by mediating toll‐like receptor 4 (TLR4)‐dependent M2 macrophage polarization of tumour‐associated macrophages." (PMID 35735103, 2022). "HMGB1 activates the TLR4/MyD88 signaling pathway in DCs and thus efficiently processes antigens associated with the presentation of dying tumor cells." (PMID 35637945, 2022). "Numerous reports suggest that TLR4 mutations and its silencing result in tumor progression, which confirm that TLR4 signaling provides protection against cancer." (PMID 34689394, 2022). "The stimulation of tumor growth by a relatively weak immune response has been claimed to be associated with the activation of TLR-4 and p38 pathway in macrophages attracted to the tumor place." (PMID 35922755, 2022). "It has been shown that TLR2 and TLR4 activation increases tumor progression by tumor-associated macrophages perhaps due to higher expression of these innate cells." (PMID 36389785, 2022). "P. anaerobius interacts with TLR2 and TLR4 on the colonocytes, and modulates tumor-associated macrophages, granulocytic tumor-associated neutrophils, and myeloid-derived suppressor cells to promote CRC." (PMID 35625485, 2022). "Genetic ablation and chemical inhibition of TLR4 signaling reduced the loss of adipose and muscle tissues and prolonged the survival of the tumor-bearing mice." (PMID 35646636, 2022). "TLR5, 7, 8, and 9 correlate with better clinical outcomes (high immune cell marker expression and/or longer survival), while TLR4, 7, and 9 are associated with poorer outcomes (advanced tumor stage, poor differenciation, and shorter survival)." (PMID 36479129, 2022).
tumor (continued). "As we know, TLR4 recognizes cathepsin K to activate the M2 polarization of tumor-associated macrophages (TAMs) through an mTOR-dependent pathway, resulting in tumor metastasis." (PMID 36204682, 2022). "It has been shown that activation of TLR4-mediated NF-κB signaling pathway in TAMs is associated with tumor growth inhibition in melanoma models." (PMID 36419877, 2022). "Since TLR4 activation is associated with tumor progression, it is also important to analyze the relation of TLR4 with clinical-pathological parameters and prognosis markers." (PMID 35327577, 2022). "Considering the importance of TLR4 in cancer pathogenesis, its expression in lichenoid lesions can result in malignant transformation susceptibility and increased tumor progression." (PMID 35327577, 2022). "Colon carcinogenesis has been associated with increased expression levels of TLR2 and TLR4, which are targets for tumour treatment." (PMID 36433652, 2022). "In contrast with the previous studies, F. nucleatum was suggested to be associated with “permissive” tumor microenvironment with low Toll-like receptor 4 (TLR4) signaling and M2 macrophage infiltration in OSCC." (PMID 36059542, 2022). "TLR4 signaling was associated with weight loss in LLC tumor-bearing mice where activation of TLR4 signaling induced the release of pro-inflammatory cytokines." (PMID 35646636, 2022). "Signaling through TLR4 induces various cytokines that have been associated with both tumor-promoting and tumor-resisting effects." (PMID 35874727, 2022). "Downregulation of TLR4 is associated with increased tumor formation and metastasis in animal models." (PMID 34844644, 2021). "We demonstrated the association among acute-phase MDSC recruitment, CXCL10/TLR4 overexpression, and tumor recurrence after small-for-size liver graft transplantation in both clinical and rat transplant studies." (PMID 33990548, 2021). "HMGB1 that is produced by tumour cells interacts with TLR4 on platelets, causing their activation, adhesion, and release of pro-metastatic factors, resulting in metastasis in mice." (PMID 34771442, 2021). "To explore the mechanism underlying the role of CAF autophagy in tumor metastasis, we first examined the effect of CAFs on TLR4/NF-κB signaling pathway." (PMID 34552063, 2021). "Activation of TLR4 signaling occurs in both MyD88-dependent and MyD88-independent pathways and associates with regulation of tumor progression and immune evasion via production of cytokines, chemokines, and type I IFNs." (PMID 34715891, 2021). "Our results corroborate other studies of tumor growth in Tlr2- and Tlr4-deficient mice, suggesting that Tlr deficiency mitigates tumor progression." (PMID 34032639, 2021). "The interaction of F. nucleatum derived LPS has been reported with TLR-4 leading to polarisation of macrophages, a process that is associated with tumour cell proliferation and metastasis." (PMID 34659241, 2021). "The tumor-associated myeloid cells were activated by symbiotic intestinal bacteria via the TLR4 signaling to produce TNF and other inflammatory cytokines, which mediate the anti-tumor effects of these drugs." (PMID 34745119, 2021). "Spearman’s rank correlation coefficient was used to analyze the relationship among TLR4 and immune neoantigens, tumor mutation burden (TMB), microsatellite instability (MSI), DNA repair genes, and DNA methylation." (PMID 34631699, 2021). "Particularly, the authors showed that polymorphism in TLR4 drives the differences in susceptibility to tumor induction by MPyV in the resistant mouse strain C57BR/cdJ (BR) in contrast to the susceptible mouse strain PERA/Ei (PEA)." (PMID 33923020, 2021). "Tenascin C binds the TLR4 to induce activation of tumor-associated macrophages and microglia and patterning towards an M2 phenotype essential for tumor growth and progression." (PMID 33805316, 2021).